ALOX15 (arachidonate 15-lipoxygenase)
Diseases named in the same sentence as ALOX15 in open-access papers (continued):
Sharing a sentence is not in itself a finding about the gene and the disease.
pregnancy disorder (1 paper, 2021). A disorder that is related to pregnancy. "The significant underexpression of ALOX15 (log2FC= −3.30) in mf-FGR placentas, accompanied by dysregulation of CYP7B1 (log2FC= −2.71) and other genes involved in inflammation, additionally underlines the role of immune response pathways in this pregnancy disorder." (PMID 33923632, 2021).
Splenomegaly (1 paper, 2022). Abnormal increased size of the spleen. "To explore whether Alox15b-KI mice suffer from splenomegaly, we compared the spleen weights of middle-aged (30–40 weeks) Alox15-KI mice and outbred wildtype controls but did not detect significant differences between the two genotypes." (PMID 35740398, 2022).
tendinopathy (1 paper, 2017). "This increase in both SPM and eicosanoids in tendon derived stromal cells from patients with tendinopathy was coupled with a significant increase in the expression of several of their biosynthetic enzymes including ALOX12, ALOX15 and PTGS2." (PMID 28887458, 2017).
thrombosis (1 paper, 2017). "To determine the in vivo relevance of 12/15-LO–mediated membrane oxidation by eosinophils during thrombotic disease, we performed an injury-induced thrombosis model in Alox15−/− mice and their WT littermates." (PMID 28566277, 2017).
cancer (89 papers, 2007 to 2026). A tumor composed of atypical neoplastic, often pleomorphic cells that invade other tissues. "In gastric cancer, cancer- associated fibroblasts secreted exo-miR-522 directly targets arachidonate lipoxygenase 15 (ALOX15) to suppress ferroptosis." (PMID 38356704, 2024). "Specifically, exosomal miR-522 secreted from cancer-associated fibroblasts (CAFs) targets arachidonate lipoxygenase 15 (ALOX15), which is a lipid peroxidation enzyme." (PMID 34830285, 2021). "Zhang’s study demonstrates that cancer-associated fibroblasts secrete miR-522 to inhibit ferroptosis through suppressing ALOX15 and decreasing the accumulation of lipid peroxidation, ultimately leading to chemoresistance." (PMID 34926441, 2021). "The current study suggested that CAF-derived exosomes play a key role in the regulation of ALOX15 expression and lipid-ROS production in cancer cells, proving that exosomes in tumor associated microenvironment are linked with ferroptosis for the first time." (PMID 32106859, 2020). "ALOX15 (a gene that encodes enzymes which act on various polyunsaturated fatty acid substrates) demonstrated a significant depot by group interaction effect (P = 0.005) with increased expression in VAT in the cancer groups compared with control (CC P = 0.018 and CWS P = 0.025, respectively)." (PMID 32232960, 2020). "These cells secrete exosomal miR-522, which inhibits cancer cell ferroptosis by targeting arachidonate 15-lipoxygenase (ALOX15) and blocking lipid peroxidation, mediating acquired chemotherapy resistance in GC." (PMID 40771798, 2025). "Endothelial cell-specific overexpression of ALOX15 in Lewis Lung Carcinoma induces necrosis and apoptosis in primary and metastatic tumors by elevating the expression of PPARγ and P21 in neighboring cancer cells in mice." (PMID 38612771, 2024). "ALOX15 is produced by some cancer cells, acting as a catalyst to convert arachidonic acid to 12[S]-HETE and 15[S]-HETE, which cause circular defects on LECs to let cancer cells enter the lymphatic vessels." (PMID 38940900, 2024). "Upon assimilation, miR‐522 reduces the expression of arachidonate lipoxygenase 15 (ALOX15), thus decreasing the lipid peroxides accumulation and resulting in chemo‐resistance of recipient cancer cells." (PMID 39611045, 2024). "This leads to the inhibition of ALOX15 and a reduction in lipid ROS accumulation in cancer cells, ultimately leading to a reduction in chemotherapy sensitivity." (PMID 38166927, 2024). "The clinical statistics illustrated that cancer-related fibroblasts (CAFs) induced the secretion of exosomal miR-522, thus inhibiting ferroptosis via ALOX15 and decreasing lipid-ROS in GC." (PMID 36701414, 2023). "Exosomal miR-522 from CAFs can inhibit ferroptosis in cancer cells by reducing ALOX15 expression and blocking lipid-ROS accumulation." (PMID 37765018, 2023). "As a key enzyme in the synthesis of the pro-inflammatory lipid mediators, ALOX15 had been widely studied in cancers, but its role on tumor progression is controversial." (PMID 36600310, 2023). "In contrast, ALOX15, an enzyme that oxidizes polyunsaturated fatty acids, has been reported to increase lipid ROS and participate in ferroptosis induction in cancer cells." (PMID 37402867, 2023). "Mammalian 15-lipoxygenases (ALOX15) are lipid peroxidizing enzymes that exhibit variable functionality in different cancer and inflammation models." (PMID 37513289, 2023). "These lesions are formed as a result of the release of the chemorepulsive compound 12-hydroxyeicosatetraenoic acid (12-(S)-HETE) by arachidonate 15-lipoxygenase (ALOX15)-expressing cancer cells." (PMID 37744339, 2023). "miR-522, secreted from CAF-derived EVs, inhibits ferroptosis in cancer by targeting arachidonate lipoxygenase 15 (ALOX15) and blocking LPO." (PMID 37700339, 2023).
cancer (continued). "The HPA transcriptome database was screened for cancer cell lines expressing high-levels of ALOX15 to use as positive controls for ALOX15 protein expression." (PMID 36010555, 2022). "The present study demonstrates that CAFs secrete exosomal miR-522 to inhibit ferroptosis in cancer cells by targeting ALOX15 and blocking lipid-ROS accumulation." (PMID 32106859, 2020). "Compared to this study, the ALOX15 gene expression has been down-regulated so that it is possible that gene expression ALOX15 whose role as an inflammatory and cancer suppressor." (PMID 32986357, 2020). "Treatment of cisplatin relatively promoted the expression of USP7/hnRNPA1 in CAFs, as well as ALOX15 in cancer cells, but the mRNA of ALOX15 remained little changed." (PMID 32106859, 2020). "We also collected primary CAFs isolated from mouse tumors, and it is clearly shown that knockdown of USP7 decreased hnRNPA1 protein levels; and the suppression of each of the three genes in CAFs lead to ALOX15 up-regulation in cancer cells." (PMID 32106859, 2020). "Our observations are consistent with previous studies which showed HDAC inhibitor-mediated transcriptional upregulation of Alox15 in colon, pancreatic and breast cancer cells." (PMID 29235036, 2018). "Cancer cells may reduce the occurrence of lipid peroxidation and ferroptosis by decreasing ALOX15 expression, thereby enhancing their own survival." (PMID 40535747, 2025). "Within this environment, there may be certain elements, such as secreted proteins or metabolites, that act to suppress the activity or expression of ALOX15 and then help cancer cells evade ferroptosis." (PMID 40535747, 2025). "Next, we examined the expression of acyl-CoA synthetase long-chain family member 4 (ACSL4), arachidonate 5-lipoxygenase (ALOX5), and arachidonate 15-lipoxygenase (ALOX15), which are implicated in lipid peroxidation, a major cause of ferroptosis in carcinoma cells." (PMID 41339896, 2025). "However, in different cancer types and in various inflammation models, ALOX15 and its PUFA metabolites exhibit dual functionality." (PMID 37513289, 2023). "Conversely, ALOX15 activators enhanced the sensitivity of cancer cells to these compounds." (PMID 37361521, 2023). "ALOX15 expression was heterogeneous and mainly located in the cytoplasm of cancer cells." (PMID 37469520, 2023). "Importantly, cisplatin and paclitaxel promote miR-522 secretion from CAFs by activating USP7/hnRNPA1 axis, leading to ALOX15 suppression and decreased lipid-ROS accumulation in cancer cells, and ultimately result in decreased chemo-sensitivity." (PMID 32106859, 2020). "Additionally, ALOX15, which was recently described to participate in the immune response in cancer, was also down regulated in KLF10 mice." (PMID 29930344, 2018). "In contrast, IDO1 (indoleamine 2,3-dioxygenase 1), which is involved in tryptophan metabolism, and ALOX15 (arachidonate 15-lipoxygenase), which regulates the metabolism of polyunsaturated fatty acids, were highly overexpressed in iPSCs compared to MSCs and cancer cell lines." (PMID 39621192, 2025). "However, the decrease of ALOX15 may be an adaptive change adopted by cancer cells to escape ferroptosis." (PMID 40535747, 2025). "It was demonstrated that this process is dependent on arachidonate 15-lipoxygenase (ALOX15) because inhibition of its activity resulted in a decrease, and overproduction caused an increase, in the sensitivity of oncogenic Ras-expressing cancer cells to erastin- and RSL3-induced ferroptosis." (PMID 33578654, 2021). "Studies have shown that in cancer cells, SAT1 expression correlates with arachidonate 15-lipoxygenase (ALOX15)." (PMID 39457099, 2024). "At the same time, by detecting the expression of AQP4-AS1, miR-4476, and ALOX15 in LUAD tissues and cancer cell lines, it was proved that AQP4-AS1 and miR-4476 were significantly highly expressed in LUAD tissues and cancer cell lines, whereas ALOX15 was expressed significantly high in normal cells." (PMID 39155888, 2024).
cancer (continued). "ALOX15 is an enzyme that transforms arachidonic acid into 12-(S)-HETE, which induces a signaling cascade that results in the retraction of LECs, the formation of CCIDs in the lymphatic walls, and the entry of cancer cells into LVs." (PMID 37744339, 2023). "In addition, both the selective ALOX15 inhibitor PD146176 and siRNA-mediated silencing of ALOX15 significantly reduced ferroptosis in erastin-induced and RSL3-induced cancer cells (e.g., HT1080, Calu-1)." (PMID 37361521, 2023). "For example, ALOX12 was seen to promote ferroptosis in cancer cells, while the ALOX15 was seen to have a role in mediating RSL3-induced ferroptosis in various cells, including neurons, and ALOX5 was also observed to be activated in erastin and RSL3-induced ferroptosis in cancer cells." (PMID 39721496, 2025).
tumor (70 papers, 2012 to 2026). "Ex vivo treatment with 12(S)-HPETE induces the cell death of aberrant hematopoietic progenitor cells from Alox15-deficient mice, suggesting the tumor-suppressive function of ALOX12." (PMID 38731802, 2024). "Blocking ALOX15 reduces the infiltration of MDSCs or monocytes, thereby decreasing the number of tumor-associated macrophages (TAMs)." (PMID 37686016, 2023). "ALOX15 promotes ferroptosis in cervical cancer by facilitating lipid peroxidation, and its expression is suppressed by tumor-associated macrophage-derived miRNA-660-5p, which inhibits ferroptosis and contributes to tumor progression." (PMID 40895556, 2025). "An interesting finding in our work was the expression of ALOX15 and its strong correlation to VN tumour size." (PMID 38480935, 2024). "Studies have shown that cisplatin and paclitaxel activate the USP7/hnRNPA1 axis to promote CAF secretion of miR-522, which inhibits the activity of ALOX15 in tumor cells, reduces ROS production, and inhibits ferroptosis in tumor cells." (PMID 39769177, 2024). "CAFs have been found to exert their protective effects on tumor cells by targeting arachidonate-15-lipoxygenase (ALOX15) and releasing cysteine and GSH to counteract oxidative stress and ferroptosis." (PMID 38853203, 2024). "Similarity, in the LUAD cell line A549 and PC9, the detection results of the expression levels of the three genes (AQP4-AS1, miR-4476, ALOX15) were consistent with the detection results in tumor tissue (p < 0.001)." (PMID 39155888, 2024). "ALOX15 and their polyunsaturated substrates can promote ferroptosis and tumor ferroptosis have been shown to be enhanced by ALOX-catalyzed lipid peroxidation in cellular membranes after induction by erastin and RSL3." (PMID 38612771, 2024). "They achieve this by inhibiting CD8+ T cell activation, upregulating PD-L1 expression in tumor cells, secreting TGF-β1, and interfering with Arachidonate 15-Lipoxygenase (ALOX15) expression, thereby promoting tumor progression." (PMID 39575419, 2024). "In this study, big data analysis revealed that PCBP1, ACSL4, and ALOX15 were differentially expressed in both tumor and normal tissues of NSCLC." (PMID 39845670, 2024). "We next examined the expression of the markers identified previously that showed good correlation with tumour volume -ALOX15, IL-1β, CSFR1, CD14 and INHBA - to their expression at the single-cell level in the macrophage subclusters." (PMID 38480935, 2024). "Endothelium-specific overexpression of human ALOX15 accelerated aortic lipid deposition in LDL-receptor deficient mice, but it also inhibited tumor growth and metastasis in two different mouse models of human cancer." (PMID 36902243, 2023). "This promotes the secretion of CAF-derived exosomal miR-522, leading to inhibition of ALOX15 and reduced lipid-ROS aggregation in tumor cells, thereby suppressing tumor chemosensitivity." (PMID 35663957, 2022). "The levels of ALOX15 and lipid ROS in tumor tissues were increased, and the tumor volume was significantly decreased." (PMID 36408273, 2022). "Among them, DDIT4 and HNF4A were highly expressed in tumor tissues, whereas ALOX15, IL33, and GDF15 were lowly expressed." (PMID 34434660, 2021). "Since miR-522 plays a key role in mediating the down-regulation of ALOX15 and lipid-ROS, resulting in suppressed cell death, we believe that miR-522 serve as the tumor-driving factor." (PMID 32106859, 2020). "The LPS injection also upregulated the ALOX15 gene (logFC = 1.71) whose product controls cytokine generation, induces the proliferation of tumor cells and the dysregulation of angiogenesis." (PMID 32545766, 2020). "Since Lipid-ROS is an important metabolite generated by ALOX15, the level of Lipid-ROS was clearly decreased in tumor tissues, and was positively related with ALOX15." (PMID 32106859, 2020). "Thus, arachidonate-15-lipoxygenase expression was positively correlated with larger tumor size, more advanced tumor stage, and vascular invasion." (PMID 41596237, 2026).
tumor (continued). "We not only detected enriched macrophages as CD68+ cells in TD-PCLS compared with healthy PCLS, but also documented the subpopulations of antitumor M1 macrophages (IL8) and tumor-promoting M2 macrophages (ALOX15 or CD206) in TD-PCLS, as to be expected for lung tumor tissue." (PMID 40728884, 2025). "Furthermore, ALOX15 expression in human sentinel lymph node metastases showed an inverse correlation with metastasis‐free survival, and knockdown of ALOX15 antagonized the formation of lymph node metastases in xenograft tumours." (PMID 38140764, 2024). "On the other hand, increasing the expression and activity of 15-LOX-1/ALOX15 throughout the body may have an anti-tumor effect against GBM, as shown by gene therapy using an adenovirus transducing the ALOX15 gene." (PMID 36765904, 2023). "In addition, a significant induction of ferroptosis-related genes (Ptgs2, Alox15 and Hmox1) was detected in tumor samples after treatment with RSL3 + iron, thus confirming the activation of the ferroptotic process inside the tumor mass." (PMID 36872341, 2023). "However, FANCD2, SLC7A11, GLS2, DPP4, and ALOX15 were obviously suppressed in grades 1–3 of tumor samples compared to normal tissues." (PMID 34531924, 2021). "Furthermore, ALOX15 is considered a tumor suppressor, since its expression or activity is frequently decreased during lung carcinogenesis." (PMID 33578955, 2021). "In summary, our study demonstrated that AQP4-AS1 can regulate the expression of ferroptosis-related regulator ALOX15 through competitive binding with miR-4476, further activating ferroptosis process and inhibiting the proliferation of LUAD tumor cells." (PMID 39155888, 2024). "Platelet-type ALOX12 and ALOX5 have been widely studied to induce carcinogenesis while ALOX15 and ALOX15B exhibit anti-carcinogenic activities although several studies demonstrate dual roles in regulating tumor development." (PMID 38612771, 2024). "ALOX15 and ALOX15B on the other hand majorly exhibit anti-carcinogenic properties, even though various studies demonstrate their dual roles in regulating tumor development." (PMID 38612771, 2024). "RT-qPCR showed expression of several macrophage markers in VS of which CD14, ALOX15, Interleukin-1β, INHBA and Colony Stimulating Factor-1R were found to have a high correlation with tumour volume." (PMID 38480935, 2024). "The expression levels of the distinct genes of the RvD pathway ALOX15, ALOX15, FPR2, GPR18, GPR32, HPGD and PTGR1 were leveraged from 516 bulk tumor HNSC RNA-seq data, profiled by TCGA and plotted as a heatmap of individual tumor samples." (PMID 35742918, 2022). "ALOX15, one of the key genes leading to ferroptosis, showed a sharp decrease, while the levels of USP7 and hnRNPA1 were clearly increased in tumor tissues." (PMID 32106859, 2020). "As shown by IHC staining, the expressions of ALOX15 and ALOX15B were strikingly down-regulated, while ALOX5 and ALOX12 were strikingly up-regulated in tumor, compared with those in surrounding tissue." (PMID 31528237, 2019). "ALOX15 has recently shown to be down-regulated in CRC and act as a tumor suppressor by promoting various anti-tumorigenic events, including cell differentiation and apoptosis, and inhibits chronic inflammation, angiogenesis and metastasis." (PMID 24643221, 2014). "In another work, we showed that the mRNA expression of ALOX15 can be detected in macrophages from tumor bearing mice and skin fibroblasts from neonatal mice, and IFN-γ can downregulate ALOX15 expression in these cells in vitro." (PMID 23818745, 2013). "While the role of ALOX15 and ALOX15B in tumor-associated macrophages (TAMs) is not yet fully understood, numerous ALOX15/B metabolites, particularly resolvins and lipoxins, exhibit anti-tumorigenic properties." (PMID 38612771, 2024).
tumor (continued). "Four ferroptosis driver genes FLT3, ALOX12B, ALOX15, and VDAC2, had a low CNV, and four ferroptosis suppressor genes ACSL3, CISD1, FANCD2, and SLC3A2, had a high CNV, indicating that ferroptosis was inhibited in tumor development." (PMID 34434214, 2021). "Second, in tumor cells, ALOX15 catalyzes the conversion of arachidonic acid to 12[S]-HETE as well as 15[S]-HETE, and these metabolites create “holes” in lymphatic endothelium facilitating tumor cell entry." (PMID 33808959, 2021). "Aspirin treatment had no impact on increased 12/15-LOX oxylipins in helminth-infected mice, supporting the hypothesis that exacerbation of tumor burden was not dependent on Hpb-increases in Alox15 expression and production of 12/15-LOX oxylipins alone." (PMID 40490052, 2025).